AKT1 (AKT serine/threonine kinase 1)
Diseases named in the same sentence as AKT1 in open-access papers (continued):
Sharing a sentence is not in itself a finding about the gene and the disease.
tumor (continued). "BCL2L11 and AKT1 have been confirmed in multiple studies to resist apoptotic signals, serving as key players in tumor cells’ defense against the immune system." (PMID 39381047, 2024). "It forms a complex with HSP70/PP2A and plays a role in tumor inhibition by blocking the AKT1 signaling pathway." (PMID 39335495, 2024). "Using our quantitative iMALDI-MS assay, we observed significant inter-tumor variability in the amount of AKT1 and AKT2 protein, with as much as a 4-fold difference among PIK3CA-mutated tumors." (PMID 38954770, 2024). "Akt1 is an important gene regulating cell survival and proliferation, which can regulate tumor proliferation, metastasis and invasion." (PMID 38994338, 2024). "Expression of radial glial cell signature genes (PAX6, SOX2, FABP7) and FGFR3 was confirmed in both the radial glial/astrocyte-like and tumor cell clusters, whereas PIK3R3 and AKT1 were only expressed in the tumor cell cluster." (PMID 38609519, 2024). "AKT1 has many roles in T-cell function and development, but in late-stage differentiated T cells, inhibition of AKT1 has been shown to enhance tumor elimination." (PMID 39689157, 2024). "AKT1 phosphorylation activates this pathway, thereby affecting tumor cell multiplication and apoptosis." (PMID 39459003, 2024). "Phosphorylated AKT1 is closely related to the growth, invasion, metastasis, apoptosis and autophagy of tumor cells." (PMID 38533261, 2024). "Tumor endothelial cells secrete IL-6 and CSF-1 which promote anti-tumor alternative macrophage polarization by triggering Akt1/mTOR pathway, resulting in anti-inflammatory and pro-tumorigenic macrophage activation." (PMID 38576482, 2024). "The anoikis-related gene DAPK2 was shown to inhibit tumor growth and metastasis through the AKT1/CyclinD1 pathway, presenting a new target for the treating of CRC." (PMID 38779664, 2024). "Recently, the identification of mutations in PIK3CA and AKT1 genes, or loss of PTEN, detected in both tissue and circulating tumor DNA, has emerged as a resistance mechanism for disease progression after first-line therapy." (PMID 39448637, 2024). "Another study demonstrated the activation of PI3K/AKT1 and ERK1 in tumor-associated macrophages (TAM) induced by co-culturing them with A2780 cells in vitro." (PMID 37675155, 2023). "In PIK3CA/AKT1/PTEN-altered tumours, this regimen was significantly beneficial, with a median PFS of 9.3 months." (PMID 37489050, 2023). "A mutation in AKT1 (E17K) was found in the MPE of MBC-PDO #04 and #07 as well as the primary tumor samples." (PMID 37509265, 2023). "We propose the upregulation of AKT1 gene expression observed in tumor tissue compared to normal tissue is due to the concomitant downregulation of miR-143-3p levels." (PMID 37759434, 2023). "The mice on the doxycycline chow had significantly reduced tumor growth compared to the regular chow-fed mice, together showing that AKT1 drives tumor cell proliferation, whereas AKT1 and AKT2 both contribute to anchorage-independent growth." (PMID 37894325, 2023). "The top-ranking genes included those that contribute to tumor development and drug resistance, such as AKT1, KLF6, and NCOR2." (PMID 37568192, 2023). "AKT1 plays a key role in cell growth and survival, and its activation in tumor is mediated by different mechanisms, including the increase in gene expression and protein phosphorylation after translation." (PMID 37623233, 2023). "Down-regulated genes belong to the class of oncogenes (Akt1, Ccnd1, Myb, and Src) and tumor suppressors (Brca1, Brca2, and Mlh1)." (PMID 37297299, 2023). "Our results show that AKT2 depletion consistently inhibits invasive and migratory behaviors, while AKT1 depletion reduces cellular proliferation and tumor growth." (PMID 37894325, 2023).
tumor (continued). "So far, biological functions of miR-149 were related to direct interactions with AKT1 or the Fas ligand, which resulted in tumor suppression in hepatocarcinoma patients or the induction of the apoptotic pathway in an acute myeloid leukemia cell line." (PMID 37324202, 2023). "In GC, for example, circNRIP1 was proven to sponge miR-149-5p to affect AKT1 expression and was transmitted in cells through exosomes, followed by enhanced tumor metastasis in PDX models." (PMID 36732659, 2023). "AKT1 gene mRNA levels were increased in the Tumor+50 mg/kg melatonin and Tumor+100 mg/kg melatonin groups compared to the Control (Tumor) group (1.83 and 1.44-fold, respectively) (p > 0.05)." (PMID 38188676, 2023). "By detecting the expression of key proteins related to signalling pathways in tumor tissue, we found that the expression levels of p-Akt1 and p-STAT3 in the HDW groups were significantly lower than those of the model group." (PMID 36647454, 2023). "We next sought to test if AKT2 knockout impaired tumor initiation when compared to AKT1 and AKT3 deletion, as our CRISPR-edited WM1799 cells exhibited more robust AKT2 deletion compared to the inducible knockdown lines, which did not impact tumor initiation." (PMID 37894325, 2023). "SRPK1 can act as a tumour suppressor by forming a complex with active AKT1 and the PHLPP1 phosphatase (alongside chaperones), which together inactivate AKT by dephosphorylating key regulatory sites." (PMID 37607329, 2023). "HSPB6 inhibits apoptosis of murine tumor cells and protects against oxidative damage, while AKT1 helps mediate cell survival and clonogenic potential." (PMID 37009487, 2023). "The present study demonstrated that downregulated or mutated ARID1A attenuates DNA HRR through stimulation of the PI3K/Akt1 pathway and makes tumor cells highly sensitive to PARPi and PARPi/ionizing radiation (IR) combination." (PMID 36910637, 2023). "USP53 deubiquitinates FKBP51, which in turn dephosphorylates AKT1 and ultimately inhibits tumor growth in LUAD." (PMID 36969062, 2023). "In summary, we demonstrated that ARID1A mutation stimulates PI3K/Akt1 pathway, attenuates DNA HRR, and makes tumor cells highly sensitive to PARPi and PARPi/IR combination." (PMID 36910637, 2023). "AKT protein, especially AKT1, enhances the survival among tumor cells after exposure to ionizing radiation by accelerating repair of double-strand breaks." (PMID 37483521, 2023). "In the current work, although cisplatin was shown to reduce tumor p-AKT-1 expression, combining it with α-hederin improved this impact." (PMID 36986504, 2023). "In GC cells, circNRIP1 acts as a tumor promotor and functions as a sponge of miR-149 to influence AKT1 expression." (PMID 37744277, 2023). "AKT1, a proto-oncogene in the serine/threonine kinase family, regulates tumor cell proliferation, survival, and metabolism through inflammation and metabolism-related signaling pathways." (PMID 37799727, 2023). "In summary, these findings showed elevated expression of AKT1 in tumor tissues compared with normal tissues." (PMID 35996134, 2022). "There were 48 intersected targets such as EGFR, AKT1, and TNF that were associated with patients’ outcomes by the univariate Cox analysis, and most of them had increased expression in the tumor as compared to normal tissues." (PMID 35873484, 2022). "Immunohistochemical assays of PI3K and AKT1 expression in tumor tissue showed that the percentages of cells positive for PI3K and AKT1 protein were lower in the LB than in the vehicle group." (PMID 36591458, 2022). "Analyses of these datasets further reveals YB-1, HIF1A, CAIX and G3BP1 transcript levels to be increased in tumours with amplified AKT1 and/or increased AKT1 expression." (PMID 34294889, 2022). "In accord with the findings in vitro, the staining frequency and intensity of BCL9L, SOX4 and AKT1 decreased significantly in downregulated‐NAT10 xenograft tumours." (PMID 35522942, 2022).
tumor (continued). "Here, we assessed the expression of mTOR, PI3K, and Akt1 on our tumor tissue sections following our treatment regimens." (PMID 35892853, 2022). "SENP3 downregulation depends on the hyper-SUMOylation of Akt1 followed by its hyper-phosphorylation and activation which is responsible for M2 polarization in the tumor microenvironment and for tumor progression." (PMID 35465332, 2022). "No false-positive result was detected and the mutations in exfoliated cells were observed only in cases showing mutations in corresponding tumours, giving a specificity of 100% for both PIK3CA and AKT1 genes." (PMID 35317488, 2022). "The results obtained from Keap1−/− and Keap1β(Keap1Δ1–31) cells unraveled that PTEN was obviously upregulated, whilst PI3K, AKT1, and mTOR were all downregulated, showing the similar trends to those of in vivo growing tumours." (PMID 36142252, 2022). "While AKT1, mTORC1, MEK1, p38 and DYRK2 can all activate HSF1, the current study indicates that activity of only AKT1 and mTORC1 maintains a strong association with HSF1 activity in tumours." (PMID 35080342, 2022). "It has been found to promote tumor cell proliferation and survival through the AKT1 and Raf–MAPK pathways." (PMID 35501919, 2022). "The protein expression of AKT1 in tumor tissues and normal kidney tissues was detected by immunohistochemical staining." (PMID 35996134, 2022). "The activity of T cells is inhibited, leading to immune escaping of tumor cells through phosphatidylinositol 3-kinase (PI3K)/AKT serine/threonine kinase 1 (AKT)/mammalian target of rapamycin (mTOR) and other signaling pathways." (PMID 35223466, 2022). "In relation to the O-GlcNAcylation regulation of Akt1, another key pathway of thyroid tumor growth is regulated by Yes-associated protein (YAP), which is a core component of the Hippo pathway, and is a tumor suppressor." (PMID 35406382, 2022). "Capivasertib, a potent selective inhibitor of all three AKT isoforms, in combination with fulvestrant shows clinical activity in patients with ER+/HER-negative BC, including those with PIK3CA/AKT1/PTEN mutant tumours." (PMID 36241868, 2022). "AKT1 is an important factor in tumor growth, and AKT2 plays an vital role in the distant metastasis of tumors." (PMID 35603567, 2022). "AKT1 plays a critical role in promoting tumor cell survival by preventing cytochrome c release from mitochondria, which is one of the important steps in the initiation of apoptosis." (PMID 35273218, 2022). "According to the boxplots analysis, tumor expression of AKT1, AKT2, and PDK1 is higher than the normal." (PMID 35634241, 2022). "Phosphorylation of AKT1 at ser473 is closely involved in cell proliferation, apoptosis and tumor growth." (PMID 36056431, 2022). "SENP3 depletion leads to increased AKT1 sumoylation in the breast cancer microenvironment, promoting macrophage polarization to the M2 subtype, which stimulates tumor growth and lymphatic metastasis." (PMID 35887358, 2022). "We proposed that CCDC65 played the role of tumor suppressor by regulating the c-Myc/ENO1/AKT1 pathway." (PMID 35844805, 2022). "By regularly sacrificing one cohort of C57BL/6J mice after HTVi, we found that exogenous Akt1 expression and the number of tumor nodules, and the size of the liver were increased with HCC progression." (PMID 36499164, 2022). "The presence of CAFs within the tumor, quantitatively depicted as FAP positivity, was strongly linked to the expression of MMP13, AKT1, TGFB3 and TGFBR2, among other factors." (PMID 35311102, 2022). "The effect of AKT1 on tumorigenesis and progression is demonstrated in a model showing that malignant tumor formation is closely related to cell infection with a retrovirus vector expressing AKT1." (PMID 35756492, 2022). "To confirm that let-7a-5p and miR-199a-5p expressions were modulated in Akt1-deficient PCa cells, we collected control and Akt1-deficient DU145 tumor colonies from the mouse lungs previously administered with these cells via the tail vein." (PMID 35406397, 2022).
tumor (continued). "AKT1 affected many functions of tumor cells, including cell proliferation, apoptosis, migration, and transcription." (PMID 35603567, 2022). "AKT1, for instance, plays a key role in regulating cell survival, insulin signaling, angiogenesis, and tumor formation." (PMID 36339598, 2022). "In another study, circNRIP1 has been shown to function as a sponge for miR-149-5p in order to regulate the level of AKT1 and subsequently play a tumor-promoting role in GC." (PMID 36338993, 2022). "For the cirReNET we built, there were many targeted genes involved in the mechanism of tumor genesis, such as AKT1, ErbB2, ITGB7, BAX, MAPK, FBXL12, CCL7 and so on." (PMID 35611168, 2022). "Authors suggest a dual role for AKT1 in tumor cell migration and invasion and highlight the cell type-specific action of Akt1 kinase in regulating cell motility." (PMID 36286049, 2022). "In BC, 50-70% of tumours contain mutations that are predicted to activate this pathway, including activating mutations in PIK3CA, a member of PI3K family, and in AKT1 genes." (PMID 35317488, 2022). "Inhibiting circ_10156 upregulated miR-149-3p, downregulated AKT1 expression, and inhibited the proliferation of tumor cells." (PMID 35741077, 2022). "We show that PRMT5 modulates AKT1 activation via direct methylation of Arg 15 and that AKT signaling regulates the expression of essential EMT-TFs that orchestrate the EMT program responsible for tumor metastasis." (PMID 35803962, 2022). "AKT1, commonly known as fuselage 1 on v-akt murine thymoma virus tumor gene, is an oncogene and is a member of the PI3K/Akt/mTOR pathway." (PMID 36286049, 2022). "It is well known that AKT1 plays an indispensable role in regulating tumor cell proliferation and apoptosis." (PMID 36523419, 2022). "Our results confirmed that PEPE2 treatment increased the Thr845 phosphorylation of ASK-1 and downregulated the ser83 phosphorylation in UBUC cells, suggesting that the PEPE2 cure likely intervented the HSP90/Akt-1/Ask-1 pathway to induce tumor cell apoptosis." (PMID 36362994, 2022). "CircNRIP1 sponged miRNA-149-5p to promote GC progression by the AKT1/mTOR pathway that exerts a positive effect on EMT to promote tumor metastasis." (PMID 35170374, 2022). "Akt1 was shown to promote tumor initiation by enhancing cell proliferation, cell survival and tumor growth, but it inhibited tumor progression." (PMID 34298660, 2021). "Akt1 participates in regulating the VEGF signaling pathway to promote tumor angiogenesis, development, and metastasis; in particular, the inhibition of Akt1 reduces the secretion of VEGF." (PMID 34394377, 2021). "In a number of tumor types, increased AKT1 activity can promote tumorigenesis and development 14-16." (PMID 34475988, 2021). "IHC tumor sections staining had a reduced expression level of proliferation marker Ki-67 and p-AKT1, because of isorhamnetin treatment." (PMID 33679411, 2021). "Apart from the known mutations, we report novel mutations in the genes AKT1, SPECC1, and LRP1B, which are linked with tumour progression and patient survival." (PMID 34796107, 2021). "The profiling data showed that 7 apoptosis-related genes were concordantly > twofold downregulated in recurrent tumor samples compared with the expression in paired primary tumor samples, including AKT1, BAG4, BCL2A1, BFAR, CARD6, CASP8 and TNFRSF21." (PMID 34488754, 2021). "Mutations in the AKT1, PIK3CA, and BRIP genes were associated with tumor recurrence, with a highly pathogenic variant in PIK3CA being particularly prominent." (PMID 34680380, 2021). "Among gene pairs tested, the combined expression of BrafV600E and Myr-Akt1 partially restored KRAS KO tumor formation in wild-type mice." (PMID 33674596, 2021).
tumor (continued). "Altogether, our data suggests PI3K likely facilitates BCC tumor growth by promoting cell cycle progression through aPKC- and Akt1-mediated p21 degradation." (PMID 34268113, 2021). "IHC in xenograft tumor tissues confirmed that p-AKT1 (Ser473) was suppressed by CCDC65 overexpression." (PMID 34335983, 2021). "It is worth mentioning that mining the data from the TargetScan database, the tumor suppressor miR-637 has other Akt isoforms as gene targets like Akt2 and Akt3 in addition to Akt1." (PMID 33911067, 2021). "Additional rescue experiments in our study indicated that AKT1 knockdown reversed the supporting role of si-ATF3 in tumor growth and immune escape in CRC." (PMID 33794833, 2021). "MAEL can be involved in ESCC progression by regulation of AKT1/RelA/IL8 signaling to recruit Myeloid-Derived Suppressor Cells (MDSCs) to tumor sites." (PMID 33902648, 2021). "Among them, the AKT1/mTOR axis is a classic metabolic pathway required to sustain tumour metabolic homeostasis." (PMID 34898043, 2021). "Sigle cell RNA sequencing of the primary tumors showed several tumor specific clusters, which were intact after Akt1 systemic deletion." (PMID 35578699, 2021). "Activated Akt2 in the same model system did not affect tumor development but caused a substantial increase in lung metastases, supporting the notion that Akt1 and Akt2 have distinct effects on tumor initiation versus tumor progression." (PMID 34298660, 2021). "When Akt1 was systemically deleted, it not only inhibited tumor growth but also markedly inhibited metastasis." (PMID 35578699, 2021). "In conclusion, this study demonstrates the relationship between NET1 and HCC progression, particularly tumor growth, invasion and metastasis, through the activation of Akt1 signaling pathway." (PMID 33839702, 2021). "ALK fusions binds to and activates PI3K through the regulatory p85 subunit of PI3K in tumor cells, leading to the phosphorylation of its downstream effectors AKT1 and AKT226." (PMID 34234236, 2021). "The antitumor effects of these NPs were tested using mouse colon cancer cells and in vivo mouse tumor models, in which it was proven that cellular uptake was enhanced and neoplasm proliferation was reduced via effective downregulation of Akt1." (PMID 34201403, 2021). "Larson found that PI3K pathway - the key pathway of tumor progression especially in phosphorylated Akt, Akt1 and Akt2, was expressed in thyroid cancer and Hashimoto’s thyroiditis, but not in normal thyroid tissues." (PMID 34993154, 2021). "MLN4924 was found to trigger epidermal growth factor receptor (EGFR) dimerization and activate EGFR downstream signaling pathways such as RAS/RAF/MEK/ERK and PI3K/AKT1/mTOR promoting tumor sphere formation and inducing wound healing in mouse models." (PMID 33572115, 2021). "Some researches have already demonstrated that circNRIP1 sponges miR-149-5p can regulate the expression level of AKT1 and act as a tumor promoter in GC." (PMID 34868391, 2021). "While Akt1 promotes vascular tumor growth, Akt3 inhibits both tumor endothelial cell growth and migration." (PMID 34419139, 2021). "The AKT1 signalling pathway plays a vital role in regulating the biological functions of tumour cell growth, proliferation, apoptosis, and metabolism." (PMID 33479376, 2021). "A recent study revealed a completely different picture of how Akt1 and Akt2 contribute to tumor development and metastasis based on systemic versus autonomous deletion of Akt1 and Akt2." (PMID 34298660, 2021).